TGFB1 (transforming growth factor beta 1)
Diseases named in the same sentence as TGFB1 in open-access papers (continued):
Sharing a sentence is not in itself a finding about the gene and the disease.
COVID-19 (continued). "The expression of TGFB1 (Transforming Growth Factor Beta 1) was found to be significantly reduced in patients with mild COVID-19 symptoms as well as those who required intensive care unit (ICU) level care, in comparison to individuals who were not affected by COVID-19." (PMID 38259635, 2023). "According to these authors, COVID-19 is associated with an inflammatory environment and strictly connected to apoptosis dysregulation, since increased level of apoptosis markers, namely CASP8, TNFSF14, TGFB1, and HGF were found compared to controls." (PMID 35269564, 2022). "In addition, TGFβ1, TGFβ3, IL-6, and IL-10 may be influential biomarkers of COVID-19 severity during the early phase of infection, whereas Th2 cytokines, IL-4 and IL-13, may be markers of persisting severity." (PMID 37569646, 2023). "Moreover, TGFβ1 may have other therapeutic advantages in fatal infectious diseases such as COVID-19, by inhibiting one of the SARS-CoV-2 attachments and point of entry, like the ACE2 receptor." (PMID 33841418, 2021). "We detected significant upregulation of the neuropilin ligand TGFB1 and chemokine CCL2 in monocytes from fatal COVID-19 cases." (PMID 41159753, 2025). "Based on relevant results reported in the existing literature and a previous study of our group, the genes CCL5, OAS1, IRF9, IFI6, TGFB1, IL1B, and TFRC were analyzed in the present study in relation to the severity of COVID-19." (PMID 38731851, 2024). "The expression of transforming growth factor beta 1 (TGFB1) and connective tissue growth factor (CTGF) was increased in alveolar epithelial cells of COVID-19 patients." (PMID 38846354, 2024). "In the present study, the differential expression of seven genes related to immunity, IRF9, CCL5, IFI6, TGFB1, IL1B, OAS1, and TFRC, was analyzed in individuals with COVID-19 diagnoses of different disease severities." (PMID 38731851, 2024). "Elevated expression of TGFB1 in CD4+ T cells and higher numbers of TGFB1-expressing T and CD14-positive cells have been observed in a small set of patients with severe COVID-19." (PMID 37255317, 2023). "While the serum proteomics showed a decrease in the levels of TGFβ1 and an increase in the levels of FN1 in COVID-19 survivors 6 months after discharge." (PMID 35288537, 2022). "The generation of NOX-dependent ROS elevates TNF-α, transforming growth factor-beta 1 (TGF-β1), ATII, and plasminogen activator inhibitor-1 (PAI-1), all of which are increased in COVID-19 patients." (PMID 35639261, 2022). "This study examined the usefulness of serum transforming growth factor-beta 1 (TGF-β1) and connective tissue growth factor (CTGF) levels in predicting disease severity in COVID-19 patients with pulmonary involvement." (PMID 35894403, 2022). "A recent study using artificial intelligence techniques revealed that genes involved in activation of immune pathways (IL-6, TNF, JAK2, IL-1B, SERPINE1, TGFB1, CD8A, and VWF) serve as major hubs in the COVID-19- thrombocytopenia interactomes." (PMID 35372456, 2022). "TGFβ1 expression was downregulated, whereas FN1 expression was upregulated in COVID-19 survivors 6 months after discharge." (PMID 35288537, 2022). "Several AD markers (CXCL10, TNFRSF1B, SPP1, TGFB1, GSTM3, and NKTR) have significantly altered expression in COVID-19 patients." (PMID 34108016, 2021). "During the period of COVID-19, HLJDD was also found to play a therapeutic role in COVID-19 through regulating multiple signaling pathways based on targeting genes such as IL6, IL10, MMP9, NOS2, VEGF, and TGFβ1." (PMID 35127697, 2021). "Interestingly in ILC1 cells, ICAM1, PIK3AP1, STAT5A, TGFB1 and FAM65B genes show the highest degree of network rewiring across healthy vs COVID-19 correlation networks." (PMID 39026668, 2024). "TGFB1 was increased in multiple CD3+ subsets including CD4+ TEMRA, CD8+ TEMRA, CD8+ EM, non-VD2 gamma-delta, and VD2 gamma-delta T cells following Foralumab treatment when compared to both healthy controls and untreated COVID-19 subjects." (PMID 36881624, 2023).
COVID-19 (continued). "The anti-inflammatory cytokine IL-10 was downregulated in pregnant and non-pregnant COVID-19 cases, whereas TGFβ1 was upregulated in both groups." (PMID 37016066, 2023). "In this study, the relative expression of IRF9, CCL5, IFI6, TGFB1, IL1B, OAS1, and TFRC genes (related to immunity and antiviral activity) was analyzed in upper airway samples from 127 individuals (97 COVID-19 positive and 30 controls) by using a two-step RT-PCR." (PMID 37389217, 2023). "Furthermore, expression levels of genes controlling cell proliferation and apoptosis, such as TGFB1, CDK4, TNFSF10, and TNFRSF10A, were also found to be dysregulated in CD4+ T cells of patients who recovered from COVID-19." (PMID 34784300, 2021). "We identified several AD marker genes (e.g., NKTR, GSTM3, TGFB1, TNFRSF1B, SPP1, and CXCL10) which may provide insights into the shared pathobiology of cognitive dysfunction in COVID-19 and AD." (PMID 34108016, 2021). "Moreover, the roles of anti-inflammatory cytokines in COVID-19 pathogenesis, including IL1R2, IL1RN, IL10, and TGFB1, are unclear and should be investigated in the future." (PMID 33101705, 2020).
non-small cell lung carcinoma (304 papers, 2010 to 2026). A group of at least three distinct histological types of lung cancer, including non-small cell squamous cell carcinoma, adenocarcinoma, and large cell carcinoma. "This protein was first described in TGFβ1-treated A549 non-small cell lung cancer (NSCLC) cells and was soon associated with corneal dystrophies, which are the only known pathological manifestations of genetic mutations in TGFBI." (PMID 20509890, 2010). "A gene expression signature (TGFβ-EMT) associated with TGFβ-induced EMT activities was developed using human Non-Small Cell Lung Carcinoma (NSCLC) cells treated with TGFβ-1 and subjected to Affymetrix microarray analysis." (PMID 30783512, 2019). "The inhibition of TGFβ1 mRNA and protein expression and the effects of the three kinds of LNPs on the proliferation of paclitaxel-resistant non-small-cell lung cancer cells (A549/T cell) were characterized." (PMID 38258086, 2024). "KLF4 inhibits cancer proliferation by stimulating the transforming growth factor beta 1 (TGF-β1)-mediated extracellular signal-regulated protein kinase/stress-activated protein kinase/NF-κB transcriptional program in non-small cell lung cancer." (PMID 36761967, 2023). "Transforming growth factor β1 (TGFβ1) has been found up-regulated in the microenvironment of various tumors, such as non-small cell lung cancer and breast cancer." (PMID 35414781, 2022). "In non-small cell lung carcinoma cells, a metabolic transition that blocks fatty acid synthesis and favors energy production has been found a crucial component of TGFβ1-induced EMT and metastasis." (PMID 35414781, 2022). "Pirfenidone, an FDA-approved drug for idiopathic pulmonary fibrosis, inhibits the production of TGFb1 and collagen, reduces tumor growth, and increases T-cell and NK-cell infiltration in murine non-small-cell lung cancer (NSCLC)." (PMID 34680381, 2021). "DEPTOR was also identified as one of the 77 clinically relevant predictive biomarker at TGFβ-EMT signature generated by microarray analysis of TGFβ-1 treated non-small cell lung cancer cells." (PMID 32998690, 2020). "Overexpressed HTRA3 inhibits the carcinogenic role of TGFβ1 and thus inhibits metastasis in the early stages of non-small cell lung cancer." (PMID 33425760, 2020). "In another study, HOXC8 levels were increased in non-small cell lung cancer and was correlated with lymph node metastasis, differences that were thought to be mediated by TGFβ1." (PMID 32366326, 2020). "In contrast, miR-142-3p was upregulated in non-small-cell lung cancer and functioned as an oncogene, and overexpression of miR-142-3p promoted cell proliferation through inhibition of TGFβ1 expression." (PMID 32047567, 2020). "It is known that high plasma level of TGFβ1 in patients with advanced non-small cell lung cancer (NSCLC) is correlated with poor prognostics." (PMID 29995950, 2018). "Lastly, cabazitaxel-loaded human serum albumin nanoparticles combined with transforming growth factor beta-1 siRNA lipid nanoparticles (CTX-HSA-NPs and TGFβ-1 siRNA LNP) were developed specifically for the treatment of paclitaxel-resistant non-small cell lung cancer." (PMID 38794306, 2024). "It is possible to treat non-small-cell lung cancer by inhibiting this aspect of the TGFB1 gene." (PMID 38791306, 2024). "Moreover, nobiletin blocked TGFβ1/Smad3 signaling to inhibit EMT in human non-small-cell lung cancer." (PMID 35458126, 2022). "MSI2 support of the expression of proteins associated with both epithelial (E-cadherin and ZO-1) and mesenchymal (TGFβ1) identity is consistent with a role of MSI2 reported previously in non-small cell lung cancer (NSCLC), in which MSI2 overexpression induced a mixed differentiation phenotype." (PMID 34237057, 2021).
non-small cell lung carcinoma (continued). "In that study, treatment of human non-small cell lung cancer cells in vitro or as xenografts with M7824 was shown to clearly attenuate features of TGFβ1–mediated mesenchymalization, including a decrease in tumor mesenchymal marker expression and chemotherapy resistance of tumor cells." (PMID 29088859, 2017). "Non-small cell lung cancer cells (A549) were stimulated with TGFβ1 (5 ng/ml) for 24 h." (PMID 25331952, 2014). "Also in A549 non-small cell lung carcinoma cells TGFβ-1 significantly induced invasion." (PMID 25744631, 2015). "We investigated whether single nucleotide polymorphisms (SNPs) at TGFβ1 were associated with overall survival (OS) and distant metastasis-free survival (DMFS) in patients with non-small cell lung cancer (NSCLC) treated with definitive radiotherapy, with or without chemotherapy." (PMID 23840350, 2013). "Bioinformatic analyses have demonstrated that EGFR, KDR, FN1, TGFB1 as well as PCNA are interacting with VEGF-A and are involved in non-small cell lung cancer tumorigenesis." (PMID 35252204, 2022). "In non-small cell lung cancer, HOXC8 acted as the transcriptional activator to strengthen TGFβ1 expression, promoting cell growth and metastasis." (PMID 33758619, 2021). "Moreover, TGFβ1 was shown to increase the expression of EMT markers N-cadherin and vimentin in the non-small-cell lung cancer cell line." (PMID 36551653, 2022).
idiopathic pulmonary fibrosis (301 papers, 2004 to 2026). Idiopathic pulmonary fibrosis (IPF) is a nonneoplastic pulmonary disease that is characterized by the formation of scar tissue within the lungs in the absence of any known cause. "Recently, Sulf-2 overexpression has also been associated with idiopathic pulmonary fibrosis (IPF), most likely through the regulation of TGFβ1 signaling in Type 2 alveolar epithelial cells." (PMID 24459635, 2014). "On the therapeutic side, two drugs, Pirfenidone (TGFβ1 inhibitor) and nintedanib (pan-tyrosine kinase FGF receptor inhibitor) have been approved for patients suffering from idiopathic pulmonary fibrosis (IPF), a form of fibrosis which does not resolve and develops in old age, mostly in men." (PMID 34307358, 2021).
myocardial infarction (276 papers, 2007 to 2026). Gross necrosis of the myocardium, as a result of interruption of the blood supply to the area, as in coronary thrombosis. "There are studies associating TGFB1 variants with heart disease, hypertension, myocardial infarction, and coronary artery disease." (PMID 37098010, 2023). "Some genetic polymorphisms of the TGFB1 gene wereshown to be associated with the severity of coronary artery atherosclerosis andgenetic predisposition to myocardial infarction; this association varies fordifferent ethnic groups." (PMID 35127145, 2021). "In a population-based study (“The Rotterdam Study”) five different TGFB1 polymorphisms (−800G/A, −509C/T, Leu10Pro, Arg25Pro, and Thr263Ile) were analyzed for correlation with myocardial infarction and stroke." (PMID 34572573, 2021). "In animal models of myocardial infarction, miR-101 is usually repressed, and delivery of miR-101 by an adeno-associated virus led to amelioration of the infarcted heart through activation of the proto-oncogene c-fos and silencing of the TGFβ1 pathway." (PMID 32517807, 2020). "As TGFβ1/Smad-mediated transcription inhibits cell proliferation in non-transformed cells, the enhancement of Smad-mediated transformation by SF would be consistent with the anticarcinogenic activity of broccoli, in addition to reduced risk of myocardial infarction." (PMID 18596959, 2008). "Baicalin improves cardiac function and myocardial fibrosis in rats with myocardial infarction, possibly through the p38 phosphorylation and TGFβ1/Smad2 pathway, exhibiting a protective effect against MI/R injury." (PMID 38659000, 2024). "Typically when myocardial infarction occurs, fibroblasts differentiate into an activated phenotype (myofibroblasts) through the activation of transforming growth factor-beta 1 (TGFβ-1) via angiotensin II (Ang II)." (PMID 35455995, 2022). "Epac1 suppression in cardiac fibroblasts is occurred after myocardial infarction and Epac1 overexpression inhibits TGFβ1-induced collagen synthesis." (PMID 30884895, 2019). "We also found and replicated biallelic combinations of TGFB1 with FGB, TGFB1 with CRP and IFNG with PTGS1 genetic variants associated with myocardial infarction providing a detectable cumulative effect." (PMID 26658659, 2015). "For example, inflammatory genes such as TNF and TGFB1 (both annotated as being important to myocardial infarction) are not included in the list of genes associated with Alzheimer’s disease on DisGeNET." (PMID 40163580, 2025). "For example, Tgfb1 and Tgfb2 mRNA abundances were decreased by sappanone A. The Tgfb family critically regulates the inflammatory response, angiogenesis, and fibrosis under myocardial infarcts." (PMID 32967328, 2020). "TGFβ1, as an important mediator of atrial fibrosis and AF, is one of the major downstream mediators of Ang II and has been fully elucidated in multiple diseases including heart failure, myocardial infarction, and hypertension, etc., in humans and in animals." (PMID 30564139, 2018). "We further detected the level of TGFβ1 in serum of myocardial infarction rats." (PMID 28266583, 2017). "In this study we found genetic variants of TGFB1, FGB and CRP genes associated with myocardial infarction in discovery and replication groups of Russian descent from the Moscow region and the Republic of Bashkortostan (325/185 and 220/197 samples, correspondingly)." (PMID 26658659, 2015). "TGFβ1 is the most representative inducer of EMT in many fibrotic diseases including liver cirrhosis, myocardial infarction, and CKD." (PMID 39887648, 2025). "Knockdown of MI-triggered upregulation of endogenous MIAT (myocardial infarction-associated transcript) reduced cardiac fibrosis and improved cardiac function via the regulation of the miR-24/furin-TGFβ-1 pathway." (PMID 37504569, 2023).
myocardial infarction (continued). "In an animal model of myocardial infarction (MI), MMP14 expressed in macrophages induced their release of TGFβ1, which subsequently resulted in activation of SMAD2-mediated EndMT pathways in nearby ECs through paracrine signaling." (PMID 34566697, 2021). "Loss of FBLN2 has been suggested to attenuate angiotensin-II signaling via a reduction of TGFβ1 activation and can further protect against ventricular dysfunction in FBLN2-null mice after myocardial infarction." (PMID 33003281, 2020). "The genetic impact of TGFB1, FGB, CRP, IFNG, and PTGS and/or their biallelic combinations on myocardial infarction was found and replicated in Russians." (PMID 26658659, 2015). "However, we consider it likely that it is the net effect of changes in several pathways, as opposed to just TGFβ1, which may underlie the observed reduction in both cancer and myocardial infarction through broccoli/crucifer consumption." (PMID 18596959, 2008). "The transforming growth factor-β1 (TGFβ1) is the main interrelated pathway involved in ASR and in the formation of atrial fibrosis in several disease conditions, including myocardial infarction, heart failure, and hypertension with upregulated Rennin-Angiotensin-Aldosterone System (RAAS)." (PMID 30564139, 2018). "Transforming growth factor beta 1 (TGF-β1) gene play an important role in the acute myocardial infarction (AMI), however no investigation has been conducted so far in young AMI patients." (PMID 18312614, 2008). "Furthermore, both TGFβ1 and IGF1 signal through the PI3K/Akt pathway and there is an extensive crosstalk between the two signalling pathways during cardiac fibrosis, cardiomyocyte apoptosis, cardiac remodelling following myocardial infarction and cardiac hypertrophy." (PMID 28509980, 2015). "CILP1 expression was determined in mouse LV infarct tissue (MI) and remote non-infarcted area (RA) at 5 days and 4 weeks following myocardial infarction and compared to connective tissue growth factor (CTGF), collagen type I (COL1A1), TGFβ1 and TGFβ3." (PMID 29167509, 2017).